FGB (fibrinogen beta chain)
Description:
Cleaved by the protease thrombin to yield monomers which, together with fibrinogen alpha (FGA) and fibrinogen gamma (FGG), polymerize to form an insoluble fibrin matrix. Fibrin has a major function in hemostasis as one of the primary components of blood clots. In addition, functions during the early stages of wound repair to stabilize the lesion and guide cell migration during re-epithelialization. Was originally thought to be essential for platelet aggregation, based on in vitro studies using anticoagulated blood. However subsequent studies have shown that it is not absolutely required for thrombus formation in vivo. Enhances expression of SELP in activated platelets. Maternal fibrinogen is essential for successful pregnancy. Fibrin deposition is also associated with infection, where it protects against IFNG-mediated hemorrhage. May also facilitate the antibacterial immune response via both innate and T-cell mediated pathways.
Synonyms: HEL-S-78p
Tractability: Small molecule: a structure with a bound ligand is known. Antibody: UniProt places it where antibodies can reach, with high confidence; its Gene Ontology location is reachable by antibodies, with high confidence; UniProt predicts a signal peptide or a membrane-spanning region. PROTAC: its protein half-life has been measured; a small molecule that binds it is known. Other modalities: an approved drug acts on it.
Target class: Secreted protein
Gene: Protein-coding gene on chromosome 4 (154,562,971 to 154,572,807, forward strand). Ensembl gene ENSG00000171564.
Subcellular location: Secreted
Subcellular location (Human Protein Atlas): Endoplasmic reticulum; Predicted to be secreted
Pathways (Reactome):
Disease: Aggregated β-amyloid interacts with fibrinogen; IRAK4 deficiency (TLR2/4); MyD88 deficiency (TLR2/4); Paradoxical activation of RAF signaling by kinase inactive BRAF; Signaling by BRAF and RAF1 fusions; Signaling by RAF1 mutants; Signaling by high-kinase activity BRAF mutants; Signaling by moderate kinase activity BRAF mutants; Signaling downstream of RAS mutants
Signal Transduction: GRB2:SOS provides linkage to MAPK signaling for Integrins; Integrin signaling; MAP2K and MAPK activation; p130Cas linkage to MAPK signaling for integrins
Immune System: ER-Phagosome pathway; MyD88:MAL(TIRAP) cascade initiated on plasma membrane; Regulation of TLR by endogenous ligand
Hemostasis: Fibrin formation; Platelet degranulation
Extracellular matrix organization: Integrin cell surface interactions
Gene Ontology:
Molecular function: cell adhesion molecule binding; extracellular matrix structural constituent; protein binding; protein-folding chaperone binding; signaling receptor binding; structural molecule activity
Biological process: blood coagulation, fibrin clot formation; cell-matrix adhesion; fibrinolysis; induction of bacterial agglutination; negative regulation of endothelial cell apoptotic process; negative regulation of extrinsic apoptotic signaling pathway via death domain receptors; plasminogen activation; platelet aggregation; positive regulation of ERK1 and ERK2 cascade; positive regulation of exocytosis; positive regulation of heterotypic cell-cell adhesion; positive regulation of peptide hormone secretion; positive regulation of protein secretion; positive regulation of vasoconstriction; protein polymerization; protein-containing complex assembly; response to calcium ion; positive regulation of substrate adhesion-dependent cell spreading; blood coagulation; cellular response to interleukin-1; cellular response to leptin stimulus; platelet activation
Cellular component: blood microparticle; cell surface; endoplasmic reticulum; external side of plasma membrane; extracellular exosome; extracellular matrix; extracellular region; extracellular vesicle; fibrinogen complex; platelet alpha granule; non-collagenous component of interstitial matrix; plasma membrane; platelet alpha granule lumen; cell cortex; synapse
Genetic constraint (gnomAD): Loss-of-function variants: 22 observed, 47.48 expected, observed/expected ratio (o/e) 0.46, 90% interval 0.33 to 0.66. The upper end of that interval is the gene's LOEUF score, 0.66, which puts it in group 2 of 6, group 1 being the genes least tolerant of losing a copy. Missense variants: 447 observed, 524.97 expected, observed/expected ratio (o/e) 0.85, 90% interval 0.79 to 0.92. Synonymous variants: 166 observed, 171.63 expected, observed/expected ratio (o/e) 0.97, 90% interval 0.85 to 1.1.
Gene-disease validity (ClinGen):
ClinGen rates the evidence that FGB causes each of these diseases.
congenital fibrinogen deficiency (semidominant): Definitive. Congenital deficiencies of fibrinogen are coagulation disorders characterized by bleeding symptoms ranging from mild to severe resulting from reduced quantity and/or quality of circulating fibrinogen.
Homologues: Orthologues: chimpanzee FGB (99% identical), macaque FGB (96% identical), dog FGB (85% identical), guinea pig FGB (85% identical), rabbit FGB (83% identical), mouse Fgb (82% identical), pig FGB (81% identical), rat Fgb (76% identical), tropical clawed frog fgb (63% identical), zebrafish fgb (53% identical). Paralogues in human: ANGPTL2 (25% identical), FGG (25% identical), TNC (24% identical), ANGPT2 (24% identical), ANGPTL1 (24% identical), ANGPTL6 (24% identical), FGL2 (24% identical), TNN (24% identical), TNR (24% identical), TNXB (24% identical), FN1 (23% identical), ANGPT1 (23% identical), and 13 more.
Diseases named in the same sentence as FGB in open-access papers:
FGB is named in the same sentence as 118 diseases in open-access papers, as found by Europe PMC text mining. Sharing a sentence is not in itself a finding about the gene and the disease. The quoted sentences say what the papers report.
COVID-19 (14 papers, 2020 to 2025). A disease caused by infection with severe acute respiratory syndrome coronavirus 2. "In our study, there was an upregulation in FGB and a downregulation in cystatins in patients with severe COVID-19 compare with those that had mild COVID-19." (PMID 35760827, 2022). "Our results revealed that tenascin-C (TNC) and fibrinogen-β (FGB) are highly abundant in exosomes from COVID-19 patients’ plasma compared with that of healthy normal controls." (PMID 33804769, 2021). "Enhanced TNC and FGB expression in exosomes isolated from COVID-19 patients was verified by Western blot analysis." (PMID 33804769, 2021). "Tenascin-C (TNC) and fibrinogen-β (FGB) were identified as the two significantly enriched molecules in exosomes from COVID-19 patients relative to normal exosomes." (PMID 33804769, 2021). "If this hypothesis is confirmed, salivary FGB could be a marker of severity in COVID-19." (PMID 35760827, 2022). "Our data also showed increased levels of fibrinogen alpha, beta, and gamma chains (FGA, FGB, and FGG) in PLWH with COVID-19 compared to those in HCs." (PMID 40568587, 2025). "We observed the higher presence of TNC/FGB in COVID-19 exosome-treated hepatocytes compared with normal exosome-treated hepatocytes, verifying the exosome-mediated uptake of TNC/FGB by hepatocytes." (PMID 33804769, 2021). "The Cox regression analyses suggested that 9 prognostic genes (ANPEP, OAS1, SCGB1A1, HLA‐A, NPPB, FGB, CCL2, TLR4, and SERPINE1) might act critical roles in the treatment of UCEC/COVID-19." (PMID 36969077, 2023). "Then, regression analyses indicated that 9 prognostic genes (including ANPEP, OAS1, SCGB1A1, HLA‐A, NPPB, FGB, CCL2, TLR4, and SERPINE1) might play important roles in quercetin for treating UCEC/COVID-19." (PMID 36969077, 2023). "Similarly, in previous reports, FGB, FGG, complements C4, C3, C5, C2, C9, and complement C1q subcomponent subunits A, B, and C (C1QA, C1QB and C1QC) were found to be upregulated in the lung tissues of patient with COVID-19." (PMID 38882332, 2024). "Additionally, the presence of FGB in patients with severe COVID-19 but not in mild COVID-19 patients could indicate a higher viral aggregation and activation in these cases." (PMID 35760827, 2022).
lung carcinoma (9 papers, 2013 to 2025). "Elevated FGB gene expression and fibrinogen levels have been linked to an increased risk of developing lung cancer and poorer prognosis in lung cancer patients." (PMID 37953225, 2023). "The first panel, consisting of FGB, FGG, and VWF proteins, exhibits promise as a diagnostic tool for the early detection of lung cancer." (PMID 37953280, 2023). "The accuracy on the Lambrechts lung cancer dataset was, however, particularly sensitive to the omittance of two genes: serum amyloid A (SAA1) and fibrinogen beta chain (FGB)." (PMID 35637521, 2022). "FGA, FGB, FGG and FGL1 were downregulated during EMT of lung cancer and were mapped to the GO term ‘Fibrinogen complex’." (PMID 24093963, 2013).
afibrinogenemia (8 papers, 2013 to 2021). "Thus, impaired secretion of fibrinogen was suggested to cause afibrinogenemia in these reported homozygous mutant FGB- and FGG-cases." (PMID 34356081, 2021). "Only two variants have been reported in position +13: the A > G transition in intron 10 of the MAPT gene, associated with familial frontotemporal dementia with parkinsonism, and the C > T transition in FGB gene’s intron 6, associated with congenital afibrinogenemia." (PMID 33245593, 2020). "Mutations in the FGB gene are especially missense or nonsense and may lead to fibrinogen deficiency by several mechanisms; these can act at the DNA level, at the RNA level or at the protein level by affecting protein synthesis, assembly or secretion." (PMID 29286337, 2017). "Similarly, studies have shown that mutations in the FGB gene could lead to afibrinogenemia, and FGB tyrosine nitration is a prothrombotic risk factor." (PMID 29416711, 2018). "Indeed there are a significant number of pathological mutations at the 3′ end of human FGB, and thus the incorporation of fibrinogen containing Fgb-eGFP into the crosslinked fibrin mesh may be simulating dys- or afibrinogenemia." (PMID 24098662, 2013). "Subnetwork 2 showed potential functional relationships between proteins FGB, FGA, APOA1, and afibrinogenemia congenital, amyloidosis familial visceral, and hypoalphalipoproteinemia." (PMID 30532734, 2018). "In this study, we performed genetic analysis of FGA, FGB and FGG genes, coagulation tests and rotational thromboelastometry in two families with quantitative congenital fibrinogen disorders (afibrinogenemia and hypofibrinogenemia)." (PMID 29286337, 2017). "Autosomal-recessive fibrinogen deficiency appears to be virtually absent in Ashkenazi Jews (no mutations found in FGA and FGB; prevalence for FGG of 1.64 per 106 individuals), whereas, non-Finnish Europeans have a predicted exceptional rate of 23.05 per 106 individuals for the sole FGG gene." (PMID 29240685, 2017).
Hypertension (8 papers, 2012 to 2023). The presence of chronic increased pressure in the systemic arterial system. "Elevated plasma FGB concentration is usually associated with hypertension and stroke." (PMID 35469231, 2022). "It is therefore unlikely that previous associations of some of the current candidates genes (VDR, FGB, AGTR1 and GPX1) with hypertension, have influenced our results, although this cannot be completely excluded." (PMID 22879966, 2012). "FGB overproduction and progress are related to high blood pressure and may even be related to the development of hypertension." (PMID 35469231, 2022).
Hypofibrinogenemia (8 papers, 2016 to 2021). Decreased concentration of fibrinogen in the blood. "Based on a presumed diagnosis of congenital hypofibrinogenemia, sequencing of the fibrinogen genes was performed, revealing a novel heterozygous mutation of FGB (Genbank NG008833); a p.403Try>Stop." (PMID 33804389, 2021). "A known (FGB p.Tyr356Cys) and a novel mutation (FGB p.Trp474*) were found in the background of hypofibrinogenemia laboratory phenotype." (PMID 33807613, 2021). "Laboratory analysis confirmed mild hyperfibrinolysis, and in both cases, a new nonsense mutation in the FGB gene was detected, leading to mild hypofibrinogenemia." (PMID 34573982, 2021). "We identified a new nonsense mutation in FGB leading to mild hypofibrinogenemia in two unrelated patients." (PMID 33322159, 2020). "Mutations accounting to hypofibrinogenemia are frequently localized in the last exon 8 of FGB, encoding the C- terminus of the βB chain." (PMID 33322159, 2020). "We identified a novel heterozygous point mutation, c.490G>A, in FGB in a 3-year-old girl with congenital hypofibrinogenemia (Kyoto IX)." (PMID 29156616, 2017). "Hypofibrinogenemia can be considered the phenotypic expression of heterozygous loss of function mutations occurring within one of the three fibrinogen genes (FGA, FGB, and FGG)." (PMID 33322159, 2020). "Most fibrinogen variants in hypofibrinogenemia are localized in the FGG gene, and only 26.6% of causative mutations are localized in the FGB gene." (PMID 33322159, 2020). "This database holds records of published variants (single‐nucleotide variants and indels) that have an impact on splicing of disease susceptibility genes (e.g., congenital hypothyroidism with SLC5A5 gene, hypofibrinogenemia with FGB gene)." (PMID 26913838, 2016). "We have sequenced all exons of the FGA, FGB, and FGG genes using the DNA isolated from the peripheral blood in two unrelated probands with mild hypofibrinogenemia." (PMID 33322159, 2020).
liver cancer (7 papers, 2013 to 2025). An epithelial or non-epithelial malignant neoplasm that arises from the liver. "We also identified a proliferative cluster, which mainly consisted of proliferating T cells and a large cluster of HCC cancer cells (40%) expressing both genes associated with normal liver function (ALB, HP, FGA, FGB) and liver cancer (AFP, SPINK1, GPC3, AKR1C1)." (PMID 38030622, 2023). "Furthermore, the levels of FGB and FGG in exosomes have shown promise as early diagnostic markers for colorectal cancer and liver cancer." (PMID 37953280, 2023). "Thus, FGA, FGB, FGG and FGL1 could be important direct target genes of FOXA1 that are involved in EMT of lung and liver cancer specifically." (PMID 24093963, 2013).
myocardial infarction (7 papers, 2010 to 2025). Gross necrosis of the myocardium, as a result of interruption of the blood supply to the area, as in coronary thrombosis. "Additionally, extracellular matrix (ECM) proteins, including vitronectin (VTN), plasminogen (PLG), and fibrinogen beta chain (FGB), displayed significant fold changes and were strongly associated with early myocardial infarction." (PMID 41399465, 2025). "In fact, high FGB levels are associated with an increased risk of coronary artery disease and the pathogenesis of myocardial infarction, and TLN1 participates in the establishment of focal cell to cell adhesions, which are characteristic in the pro-thrombotic and inflammatory process." (PMID 26152126, 2015). "We also found and replicated biallelic combinations of TGFB1 with FGB, TGFB1 with CRP and IFNG with PTGS1 genetic variants associated with myocardial infarction providing a detectable cumulative effect." (PMID 26658659, 2015). "Moreover, a multicenter longitudinal study that assessed 955 myocardial infarction survivors from six European cities identified a strong correlation between fibrinogen beta chain (FGB) and IL-6 and worse outcome after exposure to air pollutions." (PMID 31299012, 2019). "In this study we found genetic variants of TGFB1, FGB and CRP genes associated with myocardial infarction in discovery and replication groups of Russian descent from the Moscow region and the Republic of Bashkortostan (325/185 and 220/197 samples, correspondingly)." (PMID 26658659, 2015). "The genetic impact of TGFB1, FGB, CRP, IFNG, and PTGS and/or their biallelic combinations on myocardial infarction was found and replicated in Russians." (PMID 26658659, 2015).
colorectal cancer (6 papers, 2019 to 2025). A primary or metastatic malignant neoplasm that affects the colon or rectum. "The results show that FGB and C4A may be involved in pathways which are caused by advanced adenomas and subsequently colorectal cancer." (PMID 31749922, 2019). "A few DEPs have been previously reported as molecules connected with response to RT in colorectal cancer, including FGB, CD44, GLUT1/SLC2A1, PON1." (PMID 35205741, 2022). "Moreover, high expression of FGB and FGG in tumor tissue has been associated with a poorer prognosis in patients with gastric, prostate, liver, and colorectal cancers." (PMID 37953280, 2023). "Other studies reported higher levels of EVs containing glycosylated fibrinogen beta chain (FGB) and beta-2-glycoprotein 1 (β2-GP1) in plasma from patients with colorectal cancer compared to a control group." (PMID 36831450, 2023).
coronary heart disease (6 papers, 2009 to 2023). "In a prospective meta-analysis, it was found that every 1 g/L increase in FGB (β-148C/T-455G/A genotype)would double the mortality associated with coronary heart disease and stroke." (PMID 37575991, 2023). "Previous studies have found that multiple sites of the FGB gene may be related to fibrinogen expression, which are also genetic risk factors related to coronary heart disease." (PMID 37575991, 2023). "Polymorphisms of FGB was shown to be associated with coronary heart disease." (PMID 27277665, 2016).
diabetes (6 papers, 2014 to 2023). "Our results indicated that after bariatric surgery the abundance in two isoforms of FGG and one isoform of FGB increased in the control and remission groups, but not in the patients with persistent diabetes." (PMID 34501327, 2021). "From figure I, 90.6% (n=367) had normal FGB level, 9.4% (n = 38) had pre-diabetes and none was diabetic." (PMID 35222595, 2021).
dysfibrinogenemia (6 papers, 2015 to 2025). "Genetic testing confirmed the presence of a heterozygous likely pathogenic variant in FGB(c.586C > T, p.Arg196Cys), establishing the diagnosis of dysfibrinogenemia." (PMID 40757390, 2025). "Discordant activity and antigen levels, along with a pathogenic FGB variant, confirmed dysfibrinogenemia." (PMID 40757390, 2025).
ischemic stroke (6 papers, 2014 to 2023). A stroke disorder caused by obstruction of blood flow to the brain, due to thrombotic (local blood clot formation) or embolic (due to a blood clot or other material traveling from another site) event. "Other five variants associated with atherosclerosis; (viii) Beta-Fibrinogen (FGB) -455G > A; confers elevated β-fibrinogen plasma levels, which are directly related to increase the risk of acute coronary syndromes (ACS), premature MI and ischemic stroke." (PMID 28086795, 2017). "Furthermore, APOC1 is closely associated with vascular inflammation and retinitis pigmentosa, and reports have indicated that FGB is closely related to elevated plasma fibrinogen levels and ischemic stroke." (PMID 27416065, 2016).
thrombophilia (6 papers, 2018 to 2025). A condition characterized by an abnormally high level of thrombi. "Results of the present study added new information regarding the association of blood parameters and hypercoagulability in GC with the FGB and its cleaved products, which we found differentially expressed in situ in our samples." (PMID 29518939, 2018). "Furthermore, we confirmed that FGB:c.C130T: p.R44C is a mutation associated with thrombophilia." (PMID 39805289, 2025). "As key proteins in the end of EC pathway, an increase in FGA, FGB and FGG indicate that the pathway is activated and the body has developed a hypercoagulable state." (PMID 34488523, 2021).